CD44 (CD44 molecule (IN blood group))
Diseases named in the same sentence as CD44 in open-access papers (continued):
Sharing a sentence is not in itself a finding about the gene and the disease.
cancer (continued). "CD44 has been shown to be a marker of cancer stem cells and responsible for conferring tumorigenic properties to cells." (PMID 24997475, 2014). "Previous studies have revealed that the dominant form of CD44 isoforms in various tumors varies according to the location of the cancer cells." (PMID 24971320, 2014). "Markers of cancer stem cells, such as CD44 and glucose regulated protein 78 (GRP78), have been identified in HNSCCs, and cancer stem cells also contribute HNSCC tumorigenicity." (PMID 24531055, 2014). "CD44 is a transmembrane glycoprotein believed to be activated in a wide range of tumors in which it plays a critical role in cancer cell adhesion, migration, invasion and survival." (PMID 24775603, 2014). "A CD44+/CD24−/low cell population purified from cancer tissues shows the features of an EMT phenotype, and human cancer cells induced to undergo EMT exhibit a CD44+/CD24−/low antigen phenotype and high tumorigenicity." (PMID 24427168, 2014). "The floating cancer cell spheres were generated within 1 week from CD44+ cells, whereas CD44- cells started to differentiate by 3rd day of the culture." (PMID 25685059, 2014). "CD44+ cells in HCC have been suggested to be involved in the epithelial-mesenchymal transition (EMT), which is a genetic process associated with cancer invasion and metastasis." (PMID 24971320, 2014). "CD44 is also one of the most commonly studied cell surface markers, which is expressed by almost every type of cancer cells." (PMID 24581230, 2014). "For instance, CD44 glycoproteins exist in several isoforms and are expressed on epithelial and endothelial cells as well as on multiple cancer cell types such as gastric, colorectal, pancreatic, and lung cancer." (PMID 24592356, 2014). "In combination with other surface markers (e.g., ALDH and CD24), CD44 can discriminate between various cancer subsets." (PMID 24884875, 2014). "The current consensus posits that CD44+ subfractions in many human cancers are highly malignant and drug resistant." (PMID 24884875, 2014). "We have demonstrated that HNSCC contain a distinct CD24+/CD44+ cell subpopulation that possesses cancer stem cell-like properties." (PMID 24612587, 2014). "On the other hand, cancer stem cells (CSCs) are characterized as a special group of cancer cells with enhanced tumorigenicity, partial stemness as in self-renewal and differentiation, and CD44+/CD24−/low on cell surface." (PMID 24805308, 2014). "Our findings in cell lines are supported by data from breast primary cell cultures, in which lower palmitoylation and less co-localisation of CD44 with raft markers correlates with more aggressive cancers." (PMID 24512624, 2014). "Previous studies suggest that exon v10 of CD44 plays a key role in promoting cancer invasion and metastasis, however, the molecular mechanisms are not clear." (PMID 24586375, 2014). "Expression of CD44 is known to be higher in cancer stem cells than the remaining cancer cells or parental cancer cells." (PMID 24489904, 2014). "Cysteine biology has recently gained attention in terms of tumor biology because it involves reactive oxygen (ROS) production and influences the chemosensitivity of cancer cells through the CD44-xCT (cancer stem cell marker-cysteine transporter) axis." (PMID 25469504, 2014). "These CD24+/CD44+ cells derived from HNSCC cell lines displayed several features typically seen in cancer stem cells, including the ability to differentiate and self-renewal." (PMID 24612587, 2014). "In the presented study, we selected two putative cancer stem cell markers, CD44 and CD133, to compare their expression in matched primary colorectal tumor and colorectal liver metastases within clinically well-specified set of patients." (PMID 24864242, 2014). "CD44+ has identified cells with the ability of give rise to new tumors in vivo, in different types of cancer." (PMID 24775603, 2014).
cancer (continued). "CD44+ cancer cells from head and neck squamous cell carcinoma can possess properties of cancer stem cells, including cancer stem cell renewal and differentiation." (PMID 24133067, 2014). "Met is transiently activated after HGF induction and requires specific CD44 isoforms for its activation in various cancers." (PMID 24823486, 2014). "Expression of CD44, a marker linked to the CSC phenotype in some cancers, was also undetectable in the H3122 cells both before and after ALK inhibition." (PMID 25238228, 2014). "In cell starvation experiments designed to enrich for cancer stem cells, a large population with dramatically increased expression of CD44, CD44v3, CD44v6, and CD44v7 was formed." (PMID 24122205, 2014). "The aim of our pilot study was to isolate CD44+ cancer stem cells from primary cultures of OTSCC and neck node Level I (node-I) biopsies, grow cell spheres and observe their characteristics in primary cultures." (PMID 25685059, 2014). "CD44 in human cancer metastasis or prognosis has been well documented, but CD44 gene SNPs and the environmental carcinogens in HCC susceptibility and clinical features remain poorly investigated." (PMID 24971320, 2014). "Using EpCAM as an additional cell surface marker, CD44+/CD24−/low/EpCAM+ cells were demonstrated to be a more refined subpopulation with cancer stem cell properties, such as higher tumorigenic potential, self-renewal ability and tumorsphere formation." (PMID 25229616, 2014). "CD44, which localizes to the cell membrane, is reportedly involved in cell migration in various cancer types." (PMID 24519909, 2014). "Interference with the CD44-HA interaction, by targeting drugs to CD44, targeting drugs to the HA matrix, or interfering with HA matrix-CD44 interactions, are possible strategies for cancer treatment." (PMID 24642908, 2014). "CD133 and CD44 has been regarded a cancer stem-like cell marker and CD133- or CD44-positive cells play an important role in morphogenesis of ACC." (PMID 24721839, 2014). "The expression of stem cell surface markers, ALDH and CD44 were significantly low in two RhoC depleted HNSCC cell carcinoma cell lines." (PMID 24533098, 2014). "CD44 has been recently proposed to be involved in stem cell pluripotency and marks several types of cancer stem cells." (PMID 23458182, 2013). "Instead, genes that are implicated in promoting carcinogenesis control the patterns of CD44 expression in cancer cells." (PMID 23445749, 2013). "Herein, we report the development of HA-modified MR contrast agents (HA-MRCAs) for utilization in the efficient targeted detection and diagnosis of CD44-overexpressing cancer via MR imaging." (PMID 23547716, 2013). "HA-MRCAs with various ratios of HA were fabricated to determine the most efficient conditions for achieving accurate detection of CD44-overexpressing cancer." (PMID 23547716, 2013). "Here, to study the effects of CK2α on cancer stem cell maintenance via regulating Notch1, we first examined CD44 and CD24 expression after treatment with 50 μM CK2α siRNA." (PMID 23651443, 2013). "MTHFD2 knockdown resulted in impaired cell migration and invasion into extracellular matrix as well as decreased the fraction of cells with a high CD44 expression, a marker of cancer stem cells." (PMID 23295955, 2013). "On the basis of above studies, we can state that CD44 has a significant role in cancer development and prognosis." (PMID 23940692, 2013). "CD44 is expressed by hematopoietic cells, including stem and progenitor cells and cancer stem cells." (PMID 23308146, 2013). "The second known splicing target of Tra2β with likely important functions in cancer cells is within the CD44 pre-mRNA." (PMID 23935626, 2013). "Cancer stem cells are known to be CD44 positive, so this interaction is consistent with CD44 promoting cancer progression, metastasis, and chemoresistance." (PMID 23476652, 2013).
cancer (continued). "Later, it was also found that rare cancer cells possess the ability to form mammospheres enriched for highly tumourigenic CSCs of the CD44+/CD24-/low phenotype." (PMID 24229464, 2013). "CD44 is involved in several cellular processes including cell migration, survival, differentiation, and motility and is known as a cancer stem cell marker." (PMID 23308146, 2013). "Following its recent identification as a surface marker for cancer stem cells, CD44 has been applied in screening studies concerned with breast, prostate, pancreatic and head and neck cancer." (PMID 23426065, 2013). "More specifically RHAMM interacts with ERK increasing the proliferative ability of these cancer cells through a mechanism that involves the interaction of CD44 with the epidermal growth factor receptor (EGFR)." (PMID 24083250, 2013). "CD44 has also been evaluated as a cancer stem cell marker in solid tumors and in fact, served alone as a cancer stem cell marker in head and neck carcinoma." (PMID 23192764, 2013). "CD44 is a cell surface proteoglycan and glycoprotein that plays a role in cell-matrix interactions and is the principle receptor for targeted cancer therapy." (PMID 23803658, 2013). "The structural differences in the extracellular domains of the CD44 isoforms largely define a wide range of biological functions in development, inflammation, haematopoiesis, wound healing, immune response and cancer." (PMID 23565227, 2013). "Considering CD44 is the key biomarker for cancer stem cell, it is reasonable to expect the reduction in tumorigenecity." (PMID 24386318, 2013). "CD44 is overexpressed in many cancers and is involved in malignant tumor progression as well as metastasis." (PMID 23326564, 2013). "Other CD44/RHAMM networks that are associated with proliferation, growth, and cancer include MAFG, DYNLL1, MAFK, and FAM83D mediators, which are known to regulate the formation of cell mitotic spindle." (PMID 24083250, 2013). "TICs present a major obstacle in developing effective cancer treatments as many conventional therapies actually enrich for CD44+ cells." (PMID 23593654, 2013). "The percentage of cancer cells that express CD44+/CD24− phenotype correlate with spindle/mesenchymal physical features." (PMID 23401782, 2013). "CD44 plays a central role in the remodelling and degradation of hyaluronic acid, which leads to cell migration, invasion and cancer metastasis." (PMID 23295955, 2013). "This is important in that hTERT can control the cancer stem cell marker, CD44, and pSTAT3 which physically bind to CD44 in the integrated signal pathway." (PMID 24386318, 2013). "We reasoned that once STAT3 up-regulated hTERT, hTERT then started to function as an activator for CD44 in the integrated fashion which triggers the pSTAT3 signaling again, resulting in the cancer stem cell traits." (PMID 24386318, 2013). "The physicochemical properties and biocompatibilities of HA-MRCAs were fully characterized, and their enhanced sensitivity with selective binding to the CD44-abundant cancer cells was comparatively investigated via MR imaging." (PMID 23547716, 2013). "As hTERT shRNA-mediated gene silencing down-regulated cancer stem cell marker CD44 and inhibited STAT3 phosphorylation, we next examined invasiveness properties of the hTERT knocked-down cells." (PMID 24386318, 2013). "Targeted molecular imaging with hyaluronic acid (HA) has been highlighted in the diagnosis and treatment of CD44-overexpressing cancer." (PMID 23547716, 2013). "CD44 overexpression is responsible for increased survival, proliferation, migration, invasion and metastasis leading to poor prognosis among cancer patients." (PMID 23855374, 2013). "Especially, HA-MRCAs (ii) and HA-MRCAs (iii) represented a sufficiently high MR imaging sensitivity to diagnose CD44-overexpressing cancer from in vitro studies." (PMID 23547716, 2013).
cancer (continued). "Increasing evidence suggests that CD44 is a critical mediator of both growth factor- and HA-induced mitogenic and invasive signaling in cancer cells." (PMID 24069351, 2013). "CD44 is involved in cell-cell and cell-matrix interactions and signals through several pathways regulating cancer cell’s EMT, proliferation, migration and invasion." (PMID 24205138, 2013). "The responses of CD44+ GC stem-like cells to chemoradiation and the roles they play in cancer invasion are not well understood." (PMID 23833643, 2013). "CD44, a transmembrane glycoprotein, is a major receptor for extracellular proteins, including hyaluronan, involved in invasion and metastasis of human cancers." (PMID 24386318, 2013). "Then, the activated hTERT stimulates the cancer stem cell marker CD44 expression and enhances the invasiveness and migration." (PMID 24386318, 2013). "The BmHYA1 impairs the extracellular matrix receptor III (CD44) surface marker that is overexpressed in cancer cells and promotes the matrix adhesion." (PMID 23843786, 2013). "CD44, a transmembrane glycoprotein, is a major receptor for extracellular proteins involved in invasion and metastasis of human cancers." (PMID 23326564, 2013). "CD44, a receptor for HA, is closely related to the growth of cancer including proliferation, metastasis, invasion, and angiogenesis." (PMID 23547716, 2013). "We observed that activated hTERT increases CD44 (+) subpopulation, whereas targeted knock-down of hTERT abolished cancer stem cell phenotype." (PMID 24386318, 2013). "We concluded that loss of Rb function stimulated the release of presumably viable cancer cells with intact membranes (EGFP-positive) into the circulation in a CD44-dependent manner." (PMID 24324613, 2013). "During the write up of the present study, another study group successfully isolated GCSCs from the peripheral blood of cancer patients using CD44 surface markers." (PMID 23833643, 2013). "They isolated a tumorigenic subset of cancer cells from human breast tumors based on the expression of the surface markers CD44+, CD24−/low, and ESA+ (CD, cluster of differentiation; ESA, epithelial specific antigen)." (PMID 26237148, 2013). "Then, we examined the cancer stem cell phenotype and key protein expression in the CD44 knock-down cells." (PMID 24386318, 2013). "Analysis of cell surface antigens showed strong expression of cancer stem cell antigens CD44 and epithelial-specific antigen (ESA) in SKBR3 mammospheres, whereas expression of CD24, epithelial cell marker was low." (PMID 23341935, 2013). "The cancer stem cells with triple positive makers, (CD44+CD24+ESA+ cells) comprised only 1.0% of the cells in monolayers, but this value showed a statistically significant increase to 2.9% in spheroids." (PMID 24039920, 2013). "Previously, we demonstrated that expression of CD44 in feline cancer cells is cell cycle dependent and therefore it is not appropriate to utilise CD44 as a CSC marker in this species." (PMID 23219486, 2013). "Based on these results, HA-MRCAs (ii) appear to be appropriate for diagnosis of CD44-overexpressing cancer and can be utilized as drug carriers as well as in theragnosis systems using HA." (PMID 23547716, 2013). "The CD44 structure of normal cells is distinct from that of cancer cells because pathological conditions promote alternate splicing and posttranslational modifications to produce diversified CD44 molecules with increased tumorigenicity." (PMID 23533773, 2013). "We show that CD44 is expressed in nearly all cancer cells in our cell lines and CD133 is expressed in both Oct4 and nestin cell populations." (PMID 24160469, 2013). "Two-color immunofluorescent staining for CD44 and EpCAM confirmed both cancer stem cell markers co-expressed in the serial section of CLC." (PMID 23192764, 2013).
cancer (continued). "We have recently found that P-cadherin enriched cell populations show enhanced mammosphere forming efficiency (MFE), as well as increased expression of CD24, CD44 and CD49f, already described as normal or cancer stem cell markers." (PMID 23405208, 2013). "Plasmid DNA and siRNA were successfully delivered to CD44-expressing cancer cells with this approach." (PMID 23533773, 2013). "Both phenomena also suggested that CD44 is not only a marker but an essential component of metastasis-initiating cells (metastatic cancer stem cells) in BLCs." (PMID 24324613, 2013). "Of note, NSP cells also exhibited expression of CD44 protein, consistent with previously reports that CD44 is expressed in almost all cancer cells; this reflects the ambiguity of CD44 in CSC maintenance." (PMID 23776540, 2013). "Our study delineates the signaling pathway where STAT3 functions as a modulator for CD44 and hTERT, promoting a cancer stem cell phenotype." (PMID 24386318, 2013). "The most frequent histopathological type showing this CD44+/CD24- was carcinoma in mixed tumors, followed by tubular, pappilary and solid carcinomas." (PMID 24119896, 2013). "For example, expression of SLUG/SNAI2, TWIST, CD146 and Kruppel-like factor 4 (KLF4), which promote EMT and invasion, can drive cancer cells to express the CD44+/CD24−BCSC markers and exhibit BCSC phenotypes." (PMID 24977105, 2012). "The metabolic cytokine crosstalk reveals its clinical implication: CD44 as coreceptor of CD74 is also a regulatory component of the glutamate transporter xCT controlling cancer redox state." (PMID 22973314, 2012). "We also discuss CSCs differential proportionalities in various cancer cell lines and mechanisms involved in interconversion of CD44 and CD24 phenotypes." (PMID 22693526, 2012). "Intriguing studies have implicated HA/CD44 interactions in epithelial mesenchymal-transition (EMT), “stemness” and cancer." (PMID 22870202, 2012). "In contrast, siRNA silencing of CD44-encoding genes in CD44+CD24low/− cells enhanced sensitivity to doxorubicin, suggesting CD44 as a suitable target for treating cancer via gene therapy." (PMID 22400115, 2012). "CD44 is expressed on several types of cancer stem cells including breast, prostate, glioma as well as on leukemia initiating cells." (PMID 22567280, 2012). "A recent clinical study demonstrated a link between EGFR and ErbB2 inhibition and reduced CD44+/CD24low expression, the cancer stem cell marker in breast cancer." (PMID 22384257, 2012). "MiR-199a-3p has also been shown to inhibit proliferation by negatively regulating the cancer stem cell marker CD44." (PMID 23176396, 2012). "Despite intense research on CD44, the mechanism by which the protein is up-regulated in cancer and BCSCs is not well understood." (PMID 23226410, 2012). "Studies have shown that deletion of CD44 can lead to a reduction in recurrence of cancers and metastasis." (PMID 23226410, 2012). "Surprisingly, most of the colony-forming cells were positive for the cancer stem cell markers CD44 and Sca1." (PMID 22277639, 2012). "Recently, it was demonstrated that lipid rafts play a crucial role in the localization and functionality of CD44, which regulates cancer cell adhesion and migration." (PMID 22253629, 2012). "At low magnification, a distinctive distribution of the CD44/CD24 population within the cancer tissue was noted." (PMID 23028444, 2012). "CD44 is expressed on cancer cell surface and assist haematogenous spread while interacting with P- or L-selectins." (PMID 22693526, 2012). "The full molecule, often called CD44 standard (CD44S) has been found to be expressed or over expressed in a variety of cancers including EOC." (PMID 22583667, 2012). "Current experimental evidence suggests that CD44 expression characterises a subset of cancer cells with stem-cell-like properties." (PMID 22333601, 2012). "CD44 is an important marker for various cancer stem cells (CSCs), such as pancreatic, breast, ovarian, colon, and bladder CSCs." (PMID 22253629, 2012).